FSCB (fibrous sheath CABYR binding protein)
Description:
May be involved in the later stages of fibrous sheath biogenesis and spermatozoa capacitation. Inhibits ROPN1 and ROPN1L SUMOylation. Binds calcium.
Synonyms: C14orf155; DKFZP434F1017
Tractability: No criterion of Open Targets' tractability assessment is met for any kind of drug.
Gene: Protein-coding gene on chromosome 14 (44,504,149 to 44,507,283, reverse strand). Ensembl gene ENSG00000189139.
Subcellular location: Cell projection, cilium, flagellum
Subcellular location (Human Protein Atlas): Flagellar centriole; End piece; Mid piece; Principal piece
Gene Ontology:
Molecular function: calcium ion binding
Biological process: negative regulation of protein sumoylation
Cellular component: sperm fibrous sheath; sperm principal piece; motile cilium
Genetic constraint (gnomAD): Loss-of-function variants: 0 observed, 0.6 expected, observed/expected ratio (o/e) 0, 90% interval 0 to 1.82. That is too few expected variants to judge how well the gene tolerates losing a copy. Missense variants: 957 observed, 953.23 expected, observed/expected ratio (o/e) 1, 90% interval 0.95 to 1.06. Synonymous variants: 328 observed, 340.93 expected, observed/expected ratio (o/e) 0.96, 90% interval 0.88 to 1.05.
Homologues: Orthologues: macaque FSCB (77% identical), dog FSCB (43% identical), mouse Fscb (37% identical), rat Fscb (32% identical).
Diseases named in the same sentence as FSCB in open-access papers:
FSCB is named in the same sentence as 1 disease in open-access papers, as found by Europe PMC text mining. Sharing a sentence is not in itself a finding about the gene and the disease.
FSCB shares sentences with these, for which no sentence is quoted: oligospermia (1 paper).